RNU7-27P (RNA, U7 small nuclear 27 pseudogene)
Synonyms: U7.27
Gene: Small nuclear RNA gene on chromosome 7 (128,344,081 to 128,344,142, forward strand). Ensembl gene ENSG00000238750.
Homologues: Orthologues: macaque U7 (97% identical). Paralogues in human: RNU7-14P (89% identical), RNU7-21P (89% identical), RNU7-25P (89% identical), RNU7-26P (89% identical), RNU7-3P (89% identical), RNU7-11P (87% identical), RNU7-34P (87% identical), RNU7-4P (87% identical), RNU7-61P (87% identical), RNU7-7P (87% identical), RNU7-8P (87% identical), RNU7-1 (85% identical), and 143 more.